HAGHL (hydroxyacylglutathione hydrolase like)
Description:
Hydrolase acting on ester bonds.
Synonyms: MGC2605
Tractability: PROTAC: ubiquitination databases record sites on it; its protein half-life has been measured.
Gene: Protein-coding gene on chromosome 16 (726,494 to 735,525, forward strand). Ensembl gene ENSG00000103253.
Gene Ontology:
Molecular function: protein binding
Genetic constraint (gnomAD): Loss-of-function variants: 28 observed, 19.67 expected, observed/expected ratio (o/e) 1.42, 90% interval 1.05 to 1.86. The synonymous counts are far from expectation, so gnomAD's model fits this gene poorly and the ratio says little. Missense variants: 511 observed, 329.62 expected, observed/expected ratio (o/e) 1.55, 90% interval 1.44 to 1.67. Synonymous variants: 214 observed, 147.25 expected, observed/expected ratio (o/e) 1.45, 90% interval 1.3 to 1.63.
Homologues: Orthologues: dog HAGHL (87% identical), rat Haghl (83% identical), mouse Haghl (81% identical), chimpanzee HAGHL (75% identical), pig HAGHL (72% identical), guinea pig HAGHL (70% identical), tropical clawed frog haghl (60% identical), macaque HAGHL (54% identical), Drosophila melanogaster tzn (41% identical), Caenorhabditis elegans Y17G7B.3 (35% identical). Paralogues in human: HAGH (46% identical), PNKD (38% identical), ETHE1 (23% identical), MBLAC2 (17% identical).
Diseases named in the same sentence as HAGHL in open-access papers:
HAGHL is named in the same sentence as 7 diseases in open-access papers, as found by Europe PMC text mining. Sharing a sentence is not in itself a finding about the gene and the disease. The quoted sentences say what the papers report.
breast tumors (1 paper, 2023). "We obtained 5 prognosis-related genes, as the key biomarkers by Lasso-cox analysis (FBXL19, HAGHL, PHKG2, PKMYT1, and TXNDC17), all of which were significantly upregulated in breast tumors." (PMID 36747547, 2023).
paroxysmal nonkinesigenic dyskinesia (1 paper, 2021). Paroxysmal non-kinesigenic dyskinesia (PNKD) is a form of paroxysmal dyskinesia, characterized by attacks of dystonic or choreathetotic movements precipitated by stress, fatigue, coffee or alcohol intake or menstruation. "The biochemical functions of MBLAC2, hydroxyacylglutathione hydrolase-like (HAGHL), and paroxysmal nonkinesigenic dyskinesia (PNKD) proteins are still unknown." (PMID 33219126, 2021).
tumor (3 papers, 2021 to 2023). "Some CSC marker genes showed extremely disparate expression levels between normal and tumor samples, such as PLCG2, DDX11, IER5L, LENG8, HAGHL and CPNE7." (PMID 37377935, 2023).
cancer (2 papers, 2021 to 2022). A tumor composed of atypical neoplastic, often pleomorphic cells that invade other tissues. "First, there is increased conversion in cancer cells to D-lactate in the cytosol by upregulation of HAGHL, but no further conversions to oxaloacetate or acetyl-CoA." (PMID 36282866, 2022). "This possibility is intriguing considering both HAGHL and PPR7 being previously unknown for their oncogenic involvement in any cancer." (PMID 33498739, 2021).
HAGHL also shares sentences with these, for which no sentence is quoted: breast carcinoma (1 paper); Childhood Cancer (1); prostate carcinoma (1).